FOXM1 (forkhead box M1)
Diseases named in the same sentence as FOXM1 in open-access papers (continued):
Sharing a sentence is not in itself a finding about the gene and the disease.
glioblastoma (continued). "For instance, in glioblastoma stem-like cells, only ALKBH5-mediated unmethylated nascent transcripts of FOXM1 can interact with HuR to enhance FOXM1 expression and then promote self-renewal and tumorigenesis." (PMID 35093087, 2022). "An independent research study indicated that ALKBH5 was discovered to cooperate with lncRNA forkhead box protein M1 (FOXM1)-AS to accelerate tumorigenicity and proliferation of glioblastoma stem cells (GSCs)." (PMID 36226185, 2022). "STAT3 activation and the transcription factor FOXM1, which is both downstream target gene and inductor of STAT3, thus constituting an activation feedback loop, are required to promote glioblastoma CSC self-renewal and tumorigenicity." (PMID 34831207, 2021). "We demonstrated for the first time that FOXM1 contributed to aerobic glycolysis in glioblastoma and that this effect was regulated by NOX4-derived MitoROS generation, extending the role of FOXM1 as a master regulator of cancer metabolism." (PMID 34740322, 2021). "FOXM1 and E2F1, which have been shown to transcriptionally regulate RRM2 expression in prostate cancer, glioblastomas, and CRC, respectively, were also included." (PMID 34234118, 2021). "In summary, we identified for the first time that FOXM1 is a novel downstream target of NOX4-derived MitoROS, which is required for NOX4-derived MitoROS-induced aerobic glycolysis and progression in glioblastoma." (PMID 34740322, 2021). "In the present study, we found that FOXM1 and NOX4 were overexpressed in glioblastoma and established these factors as strong biomarkers for diagnosis and prognosis." (PMID 34740322, 2021). "Because intratumoral hypoxia is a common feature of solid tumors, particularly in glioblastoma, and HIF-1α is downstream of NOX4-derived ROS, we clearly elucidated that NOX4-derived MitoROS induced FOXM1 overexpression by stabilizing HIF-1α." (PMID 34740322, 2021). "Several TFs have been identified for regulating RRM2 transcription in different cancers, such as E2F1 in CRC, BRCA1 and E2F1 in glioblastoma, HPVE7 in cervical cancer, and FOXM1 in prostate cancer, and etc.." (PMID 34234118, 2021). "NOX4-induced aerobic glycolysis was dependent on elevated FOXM1 expression, as FOXM1 knockdown abolished NOX4-induced aerobic glycolysis in glioblastoma cells both in vitro and in vivo." (PMID 34740322, 2021). "FOXM1 interaction with MELK, PIN1 and pSTAT3 induced neurosphere development, BRAFV600E stimulated melanoma progression and radioresistance in glioblastoma respectively." (PMID 33680951, 2020). "Forkhead box M1 (FOXM1), which is vital for glioblastoma stem cell proliferation and tumorigenesis, is significantly upregulated by ALKBH5 via its demethylation activity on m6A." (PMID 32709063, 2020). "For example, it has been shown that FOXM1 upregulates the expression and activity of STAT3 in a β-catenin-dependent manner in glioblastoma cells." (PMID 31390744, 2019). "In glioblastoma stem cells (GSCs), an m6A demethylase, ALKBH5, was shown to interact with the lncRNA Forkhead box protein M1 (FOXM1)-AS to promote cancer cell proliferation and tumorigenicity." (PMID 31757221, 2019). "Silencing FGFR1 or FOXM1 downregulated genes involved in mesenchymal transition such as GLI2, TWIST1, and ZEB1 in glioblastoma stem-like cells." (PMID 30167084, 2018). "Our findings suggest that AKBA can arrest cell cycling at the G2/M point by regulating the p21/FOXM1/cyclin B1 pathway and that AKBA can inhibit mitosis of glioblastoma cells by down-regulating the Aurora B/ TOP2A pathway." (PMID 29970196, 2018). "The co-expression of MYBL2 and FoxM1 was analyzed in low-grade glioma (LGG) and glioblastoma (HGG) cohorts of TCGA using cBioportal and UCSC Xena." (PMID 28784180, 2017).
glioblastoma (continued). "However, Pin1 expression does not appear to significantly correlate with FOXM1, CENPF and Cyclin B1 expression in at least mammary, ovarian, renal and endometrial carcinomas and glioblastoma, suggesting the regulation of FOXM1 activity by Pin1 might be restricted to subsets of cancers." (PMID 26279295, 2016). "Additionally, in glioblastoma stem-like cells (GSCs), ALKBH5-demethylated FOXM1 nascent transcripts promote the proliferation of GSCs." (PMID 40001461, 2025). "Furthermore, we identified for the first time the binding interaction between FOXM1, AXL, and eEF2K within the glioblastoma concept." (PMID 40725039, 2025). "Recent research showed that ALKBH5 mRNA and protein expression were upregulated in glioblastoma stem-like cells (GSCs) and ALKBH5 could maintain the tumorigenicity of GSCs by maintaining FOXM1 expression." (PMID 35444654, 2022). "In glioblastoma stem cells, m6A demethylase ALKBH5 is highly expressed, which directly targets the new transcripts of FoxM1 through demethylation, thus increasing the expression of FoxM1, and promoting the stemness and proliferation of tumor cells." (PMID 35022030, 2022). "It was recently reported that in glioblastoma stem-like cells (GSCs), ALKBH5 as a m6A eraser could demethlyse FOXM1 nascent transcripts and enhanced FOXM1 expression." (PMID 35331183, 2022). "The other three RNA oligos, FoxM1-p1 (13-nt, RRACH at 3’-end), c-Myc-p5 (8-nt), and c-Myc-p6 (11-nt, RRACH at 5’-end), were derived from the FOXM1 and MYC genes because of their involvement in m6A-mediated processes in glioblastoma and acute myeloid leukemia." (PMID 35060905, 2022). "To date, whether FOXM1 is regulated by NOX4-derived ROS and the role of FOXM1 expression in glioblastoma aerobic glycolysis remain unknown." (PMID 34740322, 2021). "Since NOX4 and FOXM1 regulate aerobic glycolysis in glioblastoma cells, we asked whether NOX4 promotes the Warburg effect by upregulating FOXM1 expression." (PMID 34740322, 2021). "Increased ALKBH5 indicates poor prognosis of patients with glioblastoma while ALKBH5 depletion interferes with self‐renewal ability and inhibits the proliferation and tumorigenesis of GSCs by sustaining FOXM1 expression via ALKBH5‐mediated m6A demethylation of FOXM1 nascent transcripts." (PMID 33029866, 2020). "The glioblastoma database of the Cancer Genome Atlas, (TCGA, n = 539) was used to analyze the correlations between α6-integrin expression and several potential target genes including ZEB1, YAP1, FGFR1, and FOXM1." (PMID 30909436, 2019). "In addition, a most recent report showed that FoxM1 drives a feed-forward STAT3-activation signaling loop involved in promoting the self-renewal and tumorigenicity of glioblastoma stem-like cells." (PMID 26334131, 2015). "Overexpressing FoxM1 increased TFAM protein levels, which was reversed by FoxM1 knockdown in glioblastoma multiforme (GBM) cells." (PMID 41323781, 2025). "In summary, increased expression of BCAT1 in glioblastoma cells with preexisting high levels of expression leads to a decrease in α-KG concentration, stabilization of HIF-1α, and increased cell proliferation and invasion mediated by HIF-1α-dependent expression of FOXM1." (PMID 37885806, 2023). "The same was true for the upregulation of FOXM1 and downregulation of FOXO4 in glioblastoma multiforme (GBM)." (PMID 36292640, 2022). "In addition, recent research showed that m6A RNA methylation can regulate the self-renewal and tumorigenesis of glioblastoma stem cells, and m6A demethylase ALKBH5 can maintain tumorigenicity of glioblastoma stem-like cells by sustaining FOXM1 expression and cell proliferation program." (PMID 34054873, 2021). "This is consistent with literature data showing that FOXM1 is tightly regulated by its molecular partners that can increase FOXM1 transcriptional activity by promoting its stabilization and nuclear localization, as for instance it has been shown for the interaction with MTDH in glioblastoma." (PMID 31311575, 2019).
glioblastoma (continued). "Moreover, we have previously identified LCS1269 as a potential anti-glioblastoma agent, probably interfering with cell cycle regulation through both direct CDK1 inhibition and indirect modulation of CDK1 activity through Wee1/Myt1 and FOXM1/Plk1 signaling pathways." (PMID 40649791, 2025). "Moreover, it has recently been described that MELK interacts with the transcription factor FOXM1 (a master regulator for cell proliferation) in a Plk-1-dependent manner and that EZH2-mediated radiation resistance occurs through a MELK-FOXM1-dependent manner in glioblastoma cells." (PMID 31740676, 2019). "Finally, we analyzed existing ChIP-sequencing (seq) data from the Encode consortium, which demonstrated direct binding of FOXM1, ETS1, E2F1, and E2F6 to the EIF4EBP1 promoter region, exon 1 and intron 1 (−1500 to +1000) in various normal and cancer cells, however not including glioblastoma cells." (PMID 35228525, 2022).
ovarian carcinoma (136 papers, 2009 to 2026). A malignant neoplasm originating from the surface ovarian epithelium. "The aberrant over-expression of FOXM1 is the key molecular alteration in ovarian cancers and TNBC and is associated with chemotherapy resistance." (PMID 38697979, 2024). "Similar to observations from myeloma, breast, and ovarian cancer models, both drugs caused dose-dependent suppression of proliferation and FOXM1 expression, while altering gene expression in a manner consistent with FOXM1 inhibition." (PMID 36795481, 2023). "To test this possibility, we determined in this study how domatinostat impacts the FOXM1 pathway and cellular properties associated with the pathway, such as proliferation, survival, and sensitivity to chemotherapeutic agents, in ovarian cancer cells." (PMID 37445993, 2023). "We were unable to identify mutations in EMSY, BRIP, BARD1, and FOXM1 CNV in high-grade ovarian carcinoma as well as PTEN loss in clear cell carcinoma, LRPB1 loss and SOX17 amplification in uterine serous carcinoma." (PMID 36010253, 2022). "Recently, reports by our laboratory have demonstrated that FOXM1 is an oncogene implicated in the growth and metastasis of ovarian cancer." (PMID 36359787, 2022). "FOXM1 protein has been found to be closely associated with drug resistance, and inhibition of FOXM1 expression sensitizes cisplatin-resistant ovarian cancer cells." (PMID 36505747, 2022). "FOXM1 transcriptional targets linked to platinum resistance in ovarian cancer include exonuclease 1 (EXO1), a DNA repair protein recruited to double-stranded breaks, and PCLAF, a protein that activates the PI3K/AKT/mTOR signaling pathway." (PMID 34205406, 2021). "FOXM1 and its associated oncogenic transcriptional signature are enriched in >85% of ovarian cancer cases and FOXM1 expression and activity can be enhanced by a plethora of genomic, transcriptional, post-transcriptional, and post-translational mechanisms." (PMID 34205406, 2021). "In this study, fresh tissue specimens of 10 ovarian cancers were collected to investigate tissue cultures in their ability to predict individual treatment susceptibility and to identify the benefit of FOXM1 inhibition." (PMID 33668819, 2021). "More recently, FOXM1 had been shown to contribute to paclitaxel resistance by blocking mitosis-linked cell death in ovarian cancer cells." (PMID 33255409, 2020). "Altogether, these data indicated that RAME treatment suppressed the expression of FOXM1 target genes that were associated with enhancing cell migration in ovarian cancer cells." (PMID 33053721, 2020). "Our study shows that OTUB1, highly expressed in ovarian cancer, binds to FOXM1 and cleaves the K48-linked polyUb chain, stabilizing FOXM1 to promote tumorigenesis and tumor progression." (PMID 27167337, 2016). "We explored the potential OTUB1-catalyzed deubiquitination of FOXM1, a transcription factor linked to carcinogenesis, and the biological consequence of that interaction in ovarian cancer." (PMID 27167337, 2016). "In an analysis of 106 ovarian cancer patients, high FOXM1 levels in tumors were associated with cancer progression and short progression-free intervals." (PMID 25537512, 2015). "High nuclear FOXM1 expression in ovarian cancer patient samples was significantly associated with advanced stages (P = 0.035), shorter overall (P = 0.019) and disease-free (P = 0.014) survival." (PMID 25411964, 2014). "Higher nuclear FOXM1 expression was significantly associated with advanced stages of ovarian cancer (P = 0.035)." (PMID 25411964, 2014).
ovarian carcinoma (continued). "Our results demonstrated that casticin promotes the dephosphorylation of FOXO3a, leading to the inhibition of FoxM1, which ultimately causes ovarian cancer cell apoptosis." (PMID 23761826, 2013). "FOXM1 encodes a transcriptional activator involved in cell proliferation, and is overexpressed in various human malignancies, including ovarian carcinomas." (PMID 23029477, 2012). "Several tumorigenic assays were conducted in ovarian cancer cell models using gain- and loss-of function of FOXM1 through enforced expression of FOXM1 or inhibition of endogenous FOXM1 by thiostrepton or U0126." (PMID 21858223, 2011). "Therefore, an association has been established between FOXM1 and ovarian cancer stemness, with overexpression of FOXM1 in cisplatin-sensitive ovarian cancer cell lines promoting drug resistance." (PMID 39919692, 2025). "Our findings may also be used as a biochemical research tool to identify the molecular mechanism underlying the role of FOXM1 in ovarian cancer, as well as to assess its value as a therapeutic target in this disease." (PMID 36505747, 2022). "Therefore, the transcription factor FOXM1 is a promising target in ovarian cancer as it is frequently overexpressed and associated with poor prognosis." (PMID 33668819, 2021). "Further research on the link between FOXM1 and IAPs, which are intimately related to anti-cancer therapy resistance, may reveal additional FOXM1 transcriptional targets linked to ovarian cancer chemoresistance." (PMID 34205406, 2021). "Numerous studies have linked FOXM1 expression to poor prognosis in ovarian cancer." (PMID 34205406, 2021). "Additionally, further studies should be performed to elucidate the mechanism underlying the RAME-induced suppression of FOXM1 expression not only in ovarian cancer cells, but also in other cancer cells." (PMID 33053721, 2020). "Although FOXM1's association with high grade ovarian carcinomas has been reported, whether FOXM1 participates in the acquisition of paclitaxel resistance remains undefined." (PMID 25411964, 2014). "It has been reported that FOXM1 regulated several genes in the DNA repair pathway, we next examined whether FOXM1 knock-down cells were susceptible to DNA breaks in ovarian cancer." (PMID 24824601, 2014). "Interestingly, the concomitant increase of GRB7, ERK phosphorylation and FOXM1 is associated with high-grade ovarian cancers." (PMID 23285101, 2012). "In this study, we found that GRB7 (P<0.0001), ERK phosphorylation (P<0.0001) and FOXM1 (P = 0.001) were frequently increased and associated with high-grade tumors, as well as a high tendency in association with advanced stage ovarian cancer by immunohistochemical analysis." (PMID 23285101, 2012). "Similarly, increased phospho-ERK in concomitant with FOXM1 was significantly associated with high-grade ovarian cancer." (PMID 21858223, 2011). "Moreover, the regulatory network of the transcription factor FOXM1, known for its role as an oncogene in basal cell carcinoma, glioblastoma, breast cancer and prostate cancer, was for the first time associated with ovarian cancer." (PMID 23528888, 2013). "Clinically, BRD4 is highly expressed in ovarian cancer and independently predicts poor survival, outperforming FOXM1 and MYC." (PMID 41820523, 2026). "FOXM1 overexpression has been observed in multiple human cancers, including breast adenocarcinoma, ovarian cancer, prostate cancer, nasopharyngeal carcinoma, cervical cancer, head and neck squamous cell carcinoma and many others." (PMID 40630538, 2025).